CXCL3 (C-X-C motif chemokine ligand 3)
Diseases named in the same sentence as CXCL3 in open-access papers (continued):
Sharing a sentence is not in itself a finding about the gene and the disease.
oral cancers (1 paper, 2015). "Several chemokine ligands (chemokine (C-C motif) ligand 3 (CCL3), chemokine (C-X-C motif) ligand 2 (CXCL2), and chemokine (C-X-C motif) ligand 3 (CXCL3)) also demonstrated >25-fold overexpression in 4-NQO-induced oral cancers." (PMID 25635769, 2015). "The chemokine ligands, CCL3, CXCL2, and CXCL3, were each overexpressed by > 25-fold in NQO-induced oral cancers." (PMID 25635769, 2015).
prostate tumors (1 paper, 2022). "Quantified by ELISA, we detected that CXCL2 and CXCL3 protein levels were elevated in peripheral blood and prostate tumors of PtenPC−/−; Arid1aPC−/− mice relative to that in PtenPC−/− mice." (PMID 36435834, 2022).
Pruritus (1 paper, 2020). Pruritus is an itch or a sensation that makes a person want to scratch. "Liu found that CxCl3 was highly expressed in the cervical spinal cord of pruritus animal model, suggesting that CxCl3 may mediate pruritus." (PMID 33029266, 2020).
rectal cancer (1 paper, 2021). A primary or metastatic malignant neoplasm that affects the rectum. "Seven hub genes, including SAA1, AGT, GNG4, GAL, CXCL1, CXCL2, and CXCL3, were upregulated in rectal cancer tissues." (PMID 34269159, 2021). "CXCL1 and CXCL3, which were selected carefully from the GEO database, were the independent prognosis factors for rectal cancer." (PMID 34269159, 2021). "Results from a variety of bioinformatics analyses suggest that hub genes (CXCL1, CXCL2, and CXCL3) could be significant biomarkers for the prognosis of rectal cancer." (PMID 34269159, 2021). "Besides CXCL1, CXCL2, and CXCL3, we mined seven other hub genes related to rectal cancer, including SAA1, AGT, GNG4, SST, SSTR2, GAL, and CXCL12." (PMID 34269159, 2021). "Therefore, CXCL1 and CXCL3 may be involved in the progression of rectal cancer under the regulation of related macrophages." (PMID 34269159, 2021). "The fact that has-miR-1-3p targets three hub genes simultaneously (FDR <0.05) indicated that has-miR-1-3p could be involved in the progression of rectal cancer by regulating CXCL1, CXCL2, and CXCL3." (PMID 34269159, 2021). "It has been found that has-miR-1-3p could be involved in the progression of rectal cancer by regulating CXCL1, CXCL2, and CXCL3." (PMID 34269159, 2021). "In our study, we contend that has-miR-1-3p may affect the prognosis of rectal cancer by targeting CXCL1, CXCL2, and CXCL3." (PMID 34269159, 2021).
renal carcinoma (1 paper, 2020). A carcinoma arising from the epithelium of the renal parenchyma or the renal pelvis. "In addition, TNFα induced the upregulation of CXCL3 and its receptor in A498 renal cancer cells." (PMID 32986377, 2020).
respiratory failure (1 paper, 2020). The significant impairment of gas exchange within the lungs resulting in hypoxia, hypercarbia, or both, to the extent that organ tissue perfusion is severely compromised. "Besides expression of pro-inflammatory cytokines, such as IL-1β and TNF-α, the expression of chemokines CCL2, CCL3, CCL20, CXCL1, CXCL3, CXCL10, IL-8 was shown likely to contribute to clinical observation of excessive inflammatory tissue damage, lung injury, and respiratory failure." (PMID 33362782, 2020).
retinopathy of prematurity (1 paper, 2023). A bilateral retinopathy characterized by neovascularization, scarring, retinal detachment, and eventually blindness. "CXCL3, VEGF, CXCL5, and other inflammatory mediators were increased in DR and retinopathy of prematurity." (PMID 36658547, 2023).
skin aging (1 paper, 2023). The gradual irreversible changes in structure of skin that occur as a result of the passage of time.. "This process subsequently results in the proliferation arrest of adjacent cells such as keratinocytes through CXCL3-dependent mitochondrial ROS and induces skin aging." (PMID 37554281, 2023).
squamous cell carcinoma (1 paper, 2011). A carcinoma arising from squamous epithelial cells. "In a panel of normal/tumour matched samples, the chemokines and receptors displayed no altered expression pattern between adenocarcinoma and squamous cell carcinoma samples, with the exception of CXCL3 (average value elevated in squamous cell carcinoma and reduced in adenocarcinoma)." (PMID 21298036, 2011).
subarachnoid hemorrhage (1 paper, 2017). A serious neurological disorder characterized by intracranial hemorrhage into the subarachnoid space. "Real-time PCR data demonstrated that baicalin attenuated increased proinflammatory cytokine (IL-1β, IL-6, and CXCL-3) production in subarachnoid hemorrhage mice." (PMID 28912935, 2017).
urothelial carcinoma (1 paper, 2018). A malignant neoplasm derived from the transitional epithelium of the urinary tract (urinary bladder, ureter, urethra, or renal pelvis). "CXCL1 and CXCL3 related to the nuclear factor kappa B and nuclear factor (erythroid-derived 2)-like 2 signaling pathways were measured in human urothelial carcinoma cell lines." (PMID 29854840, 2018).
tumor (183 papers, 2011 to 2026). "Ya-Ling Qi demonstrated that CXCL3 overexpression was associated with the generation of HeLa cell tumor xenografts in athymic nude mice." (PMID 40517358, 2025). "High-risk genes (TNF, CXCL1, CCL20, ITGA5, CXCL3) typically promote tumor progression and immune evasion by inducing the expression of chemokines or modulating cellular responses to chemokines." (PMID 40517358, 2025). "In our TAME system, when CAFs were exposed to BCa cell-secreted GM-CSF, they subsequently upregulated the inflammation-associated genes IL-6, IL-6R, IL-8 and CXCL3, which support both tumor progression and CAF survival." (PMID 39199680, 2024). "These two populations expressed genes Cxcl3, Ccl3, Ccl4, Atp6v1c1, Atp6v0d2, which have been associated with a tumor promoting phenotype." (PMID 38265267, 2024). "Our results firstly indicated distinct LRs profiles between mutation-like and wildtype-like cells, where mutation-like tumor cells were specifically more likely to secret chemokines such as CXCL2/CXCL3 to communicate with other cells." (PMID 38097680, 2023). "As well as promoting tumor cell migration, CXCL3 is associated with the migration of airway smooth muscle cells and neurons." (PMID 37445610, 2023). "The results demonstrated that CXCL3-induced malignant behaviors in HT-29 and SW480 cells were predominantly restrained following blocking of ERK, suggesting an involvement of ERK signal pathway in in CXCL3-associated tumor biology in COAD." (PMID 38031087, 2023). "Chemokines were associated with the recruitment of T cells to the tumor site, and both the abnormal expression of CXCL3 and the increase in T‐cell infiltration were found in CRC complicated with DM in this study." (PMID 36999930, 2023). "When some types of cancer cells fail to express CXCL3 highly, the degree of tumor malignancy and the risk of patients are increased." (PMID 37161430, 2023). "In the mouse tumor tissues, Trim11 deficiency also upregulates the expression of Cxcl1, Cxcl2 and Cxcl3." (PMID 36192394, 2022). "C-X-C motif chemokine ligand 3 (CXCL3), as a member of the chemokine family, has been found to be closely associated with tumor formation via the Erk pathway." (PMID 36345403, 2022). "It was also shown that IL33-stimulated tumour-associated macrophages (TAMs) were the primary source of CXCL3, and that CXCL3 and IL33 were correlated with poor survival." (PMID 36358721, 2022). "Chemotactic cytokines involved in the immune response include CXCL1, CXCL3, and CXCL3, which are closely associated with tumor transformation and angiogenesis." (PMID 34442627, 2021). "CXCL3 was associated Tumour, Node, Metastasis stage and differentiation, which are associated with prognosis." (PMID 32376891, 2020). "We also report an overexpression of CXCL3, both at the RNA and protein levels, associated with tumour stage and differentiation." (PMID 32376891, 2020). "The authors reported that CXCL3 over-expression was associated with advanced tumor stage, lymphatic invasion, and distant metastases." (PMID 31213644, 2019). "HCC patients with higher CXCL3 expression displayed a poor prognosis, and a high level of CXCL3 was significantly associated with vascular invasion and tumor capsule formation." (PMID 27255419, 2016). "CXCL1, CXCL2 and CXCL3 are positively associated with tumor associated angiogenesis and depletion of these three chemokine factors have inhibited the tumor growth in mice." (PMID 26303932, 2015). "In vivo, IL-27 hampered both AC and SCC tumor growth in association with a prominent granulocyte- and macrophage-driven colliquative necrosis, CXCL3 production, and a reduced pluripotency- and EMT-related gene expression." (PMID 25638163, 2015). "We hypothesized that interference with Cxcl3 and Ccl20 may cause differences in T-cell immune function, which may influence tumor formation." (PMID 40179015, 2025).
tumor (continued). "Furthermore, this growth suppression was accompanied by decreased tumor angiogenesis, reduced expression of the neutrophil chemoattractant CXCL3, and a lower number of tumor‐associated neutrophils (TANs)." (PMID 40751595, 2025). "CXCL3 is the key cytokine of tumor immunosuppression caused by microbiota dysbiosis in CRC." (PMID 40179015, 2025). "Activation of CXCR2 by CXCL3 promoted a phenotypic transition from fibroblasts to myofibroblast-like cancer-associated fibroblasts, marked by α-smooth muscle actin expression, ultimately promoting tumor metastasis." (PMID 41259383, 2025). "In both in vitro cell experiments and in vivo xenograft tumor models, CXCL3 overexpression led to elevated protein levels of PI3K, p-PI3K, AKT, p-AKT, mTOR, and p-mTOR compared to mock controls." (PMID 41259383, 2025). "The CRNDE - NF-κB - CXCL3 axis plays an important role in promoting the immunosuppressive environment and tumor progression in HCC." (PMID 40352941, 2025). "Studies have shown that CXCL3 promotes tumor progression by activating signaling pathways such as ERK/MAPK in the TME." (PMID 40179015, 2025). "CXCR2 is not only activated by CXCL1 but also by several other CXC chemokines, including CXCL2, CXCL3, CXCL5, CXCL6, and CXCL8, all of which are closely associated with cancer progression and the tumor microenvironment." (PMID 40490643, 2025). "Our observations suggest CXCL3 is a major chemotactic factor affecting the tumor immune microenvironment in mouse models of imbalanced microbiota and can attract PMN-MDSCs that express CXCR2 receptor, rather than M-MDSCs." (PMID 40179015, 2025). "Previous studies have demonstrated that tumor cells secrete cytokines, including IL-6 and CXCL3, among others, to facilitate the recruitment of MDSCs into the TIME." (PMID 41326342, 2025). "Chemokines and cytokines such as CSF2, CCL12, CCL20, IL1B, and CXCL3/5/6 are significantly upregulated in the tumor microenvironment, indicating that the body is extensively recruiting and activating myeloid immune cells." (PMID 41415031, 2025). "Given the important role of CXCL3 in promoting the formation of an immunosuppressive microenvironment, our research focused on exploring the impact of metabolites on the tumor immune microenvironment, with a particular emphasis on the cytokine CXCL3." (PMID 40179015, 2025). "To confirm the inhibition of tumor growth associated with decreased chemokine expression in Ccn1‐KO tumor, we focused on CXC chemokines, including CXCL1, CXCL3, and CXCL5, which bind to CXCR2, as well as CCL2 and CCL7, which bind to CCR2." (PMID 40287974, 2025). "Specifically, CXCL3 drives the transformation of CAFs into myofibroblastic CAFs, facilitating tumor metastasis, whereas CXCL8 promotes tumor cell proliferation, EMT, and an immunosuppressive tumor microenvironment." (PMID 40725006, 2025). "The results confirmed that the mRNA expression levels of Cxcl1 and Cxcl2 were decreased in Il7r-KO tumor cells, while the expression of Cxcl3 remained unchanged." (PMID 41360767, 2025). "To explore the immune response of CCL20 and CXCL3, we constructed stable knockdown of Ccl20 and Cxcl3 in orthotopic implanted tumor mouse models." (PMID 40179015, 2025). "SiglecF-high and Cxcl3-high neutrophils were previously reported exclusively in tumor-bearing tissues." (PMID 41322421, 2025). "High expression of the ligands of Cxcr2, such as Cxcl1, Cxcl2, Cxcl3, and Cxcl5, was observed mainly in tumor cells, fibroblasts, chondrocytes, pericytes and osteoclasts among APM‐naïve cells." (PMID 40433925, 2025). "CXCR2, the receptor for CXCL3 and CXCL5, has been associated with promoting cellular processes such as tumor cell proliferation, migration, invasion, angiogenesis, lymphangiogenesis, and cellular senescence." (PMID 38365809, 2024).
tumor (continued). "The interplay between UPP1high tumor cells and SPP1+ macrophages was linked with a variety of chemokines, including CCL2_CCR2, CCL3_CCR5, CXCL3_CXCR2, and CXCL8_CXCR1, as well as interactions such as IL1B_IL1_receptor and TGFB1_TGFbeta_receptor1." (PMID 38331898, 2024). "We identified pro-inflammatory cytokines (IL1A, IL1B, IL6), and chemokines (CCL3, CXCL2, CXCL3) that promote inflammation-promoted neoplasia." (PMID 38529274, 2024). "Blocked Cxcl3 by anti-Cxcl3 effectively abrogated Crnde induced tumor growth, and G-MDSCs migration in vivo and vitro." (PMID 38169579, 2024). "Together, these findings demonstrate that CRNDE-mediated CXCL3 secretion is an important factor in promoting tumor growth and G-MDSCs recruitment." (PMID 38169579, 2024). "To elucidate the factors governing G-MDSC recruitment in CRNDE-induced HCC, we examined putative G-MDSC-recruiting chemokines, indicating that the expression of Cxcl3, Cxcl1, Cxcl5, and Ccl2 was significantly increased in upregulated Crnde tumor cells." (PMID 38169579, 2024). "Specifically, the proportions of COL1A1+ macrophages and GZMA+ macrophages deceased in tumor groups, while CXCL3+ macrophages appeared exclusively in tumor samples." (PMID 39112478, 2024). "In particular, several well-known inflammatory factors in tumor microenvironment, including IL-8, IL-1, IL-12, and CXCL3, were significantly elevated in the miR-182-overexpressing cells relative to NC-infected cells." (PMID 37127752, 2023). "Recently, numerous evidence indicated that CXCL3 is broadly expressed in various human tumor types, and it is also known to play a critical role in mediating tumor development and progression." (PMID 38031087, 2023). "In vitro, exogenous administration or overexpression of CXCL3 resulted in increased malignant behaviors of HT-29 and SW480 cells, and down-regulation of CXCL3 expression inhibited the malignant behaviors of these tumor cells." (PMID 38031087, 2023). "RT-qPCR results showed that tumor tissues exhibited significantly higher expression levels of CXCL3 and CXCL6 mRNAs compared with matched normal tissues, which were in line with the results from the UALCAN database." (PMID 37161430, 2023). "Chronic stress promotes CXCL2/CXCL3 secretion of tumor cells, induces CXCR2 expression of myeloid cells, and thus facilitating spleen myeloid cells movement into tumor tissue through the CXCL2/CXCL3-CXCR2 axis." (PMID 36707854, 2023). "M1‐TAMs are associated with inflammatory factors, including CCL2/3/4, CXCL3, and TNF, which recruit T cells, immature DCs, and NK cells in the tumor microenvironment." (PMID 36529697, 2023). "CXCL3 has many essential functions, including leukocyte chemotaxis, promotion of angiogenesis and tumor development, immune regulation, and interactions with other cytokines to form connections between inflammation, immune regulation, and tumorigenesis." (PMID 35664357, 2022). "CXCL3 is closely related to tumor growth and can affect the proliferation, invasion, and migration of tumor cells by activating relevant cell pathways in combination with their receptors." (PMID 35802745, 2022). "Another strongly expressed gene found in tumour tissue was CXCL3, a proinflammatory cytokine ligand related to immunological processes, consistent with previous observations." (PMID 36077612, 2022). "CXCL3 interaction with its cognate receptor activates neutrophils to secrete cytokines that promote angiogenesis, one of the most essential steps in tumor development." (PMID 35664357, 2022). "CXCR2, the CXC receptor expressed by neutrophils, can bind with its ligand chemokine family (CXCL1, CXCL2, CXCL3, CXCL5, CXCL7, and CXCL8) to recruit neutrophils to the TME and participate in the mobilization of tumour-associated neutrophils." (PMID 36743929, 2022). "An increasing number of studies suggest that CXCL3 can serve as a novel predictor of tumor progression." (PMID 35802745, 2022).